MGMT (O-6-methylguanine-DNA methyltransferase)
Diseases named in the same sentence as MGMT in open-access papers (continued):
Sharing a sentence is not in itself a finding about the gene and the disease.
ovarian carcinoma (18 papers, 2003 to 2024). A malignant neoplasm originating from the surface ovarian epithelium. "An opposite behavior of the overall survival curves was found for MGMT gene, probably due to its different association in specific histotypes of ovarian carcinoma." (PMID 29882921, 2018). "The pooled OR indicated that MGMT promoter methylation was significantly linked to pathological types in ovarian cancer (OR = 0.29, 95% CI = 0.14–0.59, p = .001), including five studies with 185 serous cancer and 155 nonserous cancer patients." (PMID 29195029, 2018). "The result demonstrated that MGMT promoter methylation was notably correlated with an increased risk of ovarian cancer in the comparison of ovarian cancer patients and normal ovarian tissues (OR = 4.13, 95% CI = 2.32–7.33, p < .001)." (PMID 29195029, 2018). "Furthermore, hypermethylation of other DNA damage repair pathway-related genes, like GSTP1, FANCF, and MGMT, has been described to be positively associated with chemosensitivity in ovarian cancer patients." (PMID 28641578, 2017). "For MGMT-methylated breast and ovarian cancer patients, a family history of cancer was determined in 113 patients out of the 156 MGMT-positive cases." (PMID 38542081, 2024). "As a result, constitutive MGMT promoter methylation, like BRCA1, is a potential diagnostic biomarker for breast and ovarian cancer risk." (PMID 38542081, 2024). "In this study, we assessed the contribution of BRCA1 and MGMT epimutations to breast and ovarian cancer in women from Saudi Arabia." (PMID 38542081, 2024). "This meta‐analysis was first conducted to estimate the clinical significance of MGMT promoter methylation in ovarian carcinoma." (PMID 29195029, 2018). "MGMT promoter methylation had s similar frequency in ovarian carcinoma versus LMP and benign lesions." (PMID 29195029, 2018). "Nevertheless, data with regard to the methylation levels of the MGMT promoter were inconsistent in ovarian cancer." (PMID 29195029, 2018). "Subgroup analysis of detection method demonstrated that MGMT promoter methylation was correlated with ovarian cancer in the MSP and non‐MSP subgroups." (PMID 29195029, 2018). "MGMT promoter methylation was significantly higher in ovarian cancer than in normal ovarian tissues (OR = 4.13, 95% CI = 2.32–7.33, p < .001)." (PMID 29195029, 2018). "The DNA repair genes BRCA1, MLH1, and MGMT were among those genes affected by hypermethylation in ovarian cancer." (PMID 23344037, 2013). "Furthermore, 36% of the BRCA1-methylated patients and 34.5% of the MGMT-methylated patients had a family history of cancer, including breast and ovarian cancer." (PMID 38542081, 2024). "Here, we sought to see whether there was a link between BRCA1- and MGMT-methylated breast and ovarian cancer and each patient’s family history of cancer." (PMID 38542081, 2024). "Additionally, we aimed to determine the roles of constitutional BRCA1 promoter methylation and MGMT promoter methylation in the incidence of ovarian cancer in Saudi women." (PMID 38542081, 2024). "The DNA methylation of BRCA1 and MGMT has been previously reported in ovarian cancer." (PMID 35008168, 2021). "The association between promoter methylation of the MGMT gene and its expression was found in ovarian cancer, with negative MGMT expression." (PMID 29195029, 2018). "Moreover, 10 of 67 (15%) breast and 17 of 82 (20.7%) ovarian cancer patients were positive for MGMT methylation." (PMID 30049288, 2018). "On the basis of numerous studies with small sample size and the different methylation frequencies, we carried out this meta‐analysis to better determine the relationship between the methylation of the MGMT promoter and ovarian cancer in the comparison of cancer and different control groups." (PMID 29195029, 2018).
ovarian carcinoma (continued). "The result showed that ovarian cancer had a significantly higher methylation status of MGMT promoter than normal ovarian tissues, which suggested that MGMT promoter methylation may be an early event of the carcinogenesis of ovarian cancer." (PMID 29195029, 2018). "However, the relationship between MGMT promoter methylation and ovarian cancer remains controversial." (PMID 29195029, 2018). "In summary, our findings suggested that MGMT promoter methylation may play a crucial role in the initiation of ovarian cancer." (PMID 29195029, 2018). "This gene is involved in the repair of DNA damages and hypermethylation is observed in several neoplastic and preneoplastic conditions Recently, a meta-analysis that evaluated the samples of 10 ovarian cancer studies showed the importance of MGMT methylation in ovarian cancers." (PMID 29882921, 2018). "Importantly, five of the 13 (38.5%) BRCA1 methylation-positive ovarian cancer patients had methylated MGMT gene." (PMID 30049288, 2018). "The methylation rate of MGMT promoter ranged from 0% to 38.9% in ovarian carcinoma." (PMID 29195029, 2018). "Thus, we performed this study using eligible publications to further identify the relationship between the methylation of MGMT promoter and ovarian carcinoma." (PMID 29195029, 2018). "Our study confirms the high occurrence of MGMT methylation in ovarian cancers." (PMID 29882921, 2018). "MGMT promoter methylation may be correlated with the tumorigenesis of ovarian cancer." (PMID 29195029, 2018). "Furthermore, MGMT promoter methylation and the lack of MGMT expression were found to be associated with the mucinous and clear cell subtypes of epithelial ovarian cancer." (PMID 30049288, 2018). "In ovarian cancer, MCL1 is stabilized by MGMT-activated DUB3, leading to resistance to platinum/paclitaxel-based chemotherapy in ovarian cancer cells." (PMID 38254819, 2024). "We conducted a comprehensive analysis of a group of 1958 Saudi women, comprising breast and ovarian cancer patients and controls, to determine the prevalence of BRCA1 and MGMT epimutations." (PMID 38542081, 2024). "Three studies well defined in ovarian cancer includes: Methylation of either BRCA1, GSTP1, or MGMT significantly correlates with improved response to chemotherapy (p = 0.013)." (PMID 31608277, 2019). "In order to value the epimutation of MGMT and BRCA1 in WBC from cancer-free women and newborns, we investigated the prevalence of the methylated BRCA1 and MGMT promoters in breast and ovarian cancer patients." (PMID 30049288, 2018). "Subgroup analysis of ethnic population showed that the methylation status of MGMT promoter was associated with ovarian carcinoma in the Caucasian and mixed populations, but not in Asian population, suggesting that the MGMT may be a susceptible gene for Caucasians and mixed population." (PMID 29195029, 2018). "APC, CDH13, CRABP1, HOXA9, HOXB5, RASSF1A, and SCGB3A1 were found to be hypermethylated both in the primary tumours and in ovarian cancer cell lines, whereas ADAMTS1 and MGMT were hypermethylated only among cell lines." (PMID 17623056, 2007). "Although methylation of MLH1 and MGMT was uncommon in the present study, we cannot rule out that epigenetic inactivation of DNA repair genes may be a mechanism associated with specific subtypes of ovarian cancer." (PMID 17623056, 2007). "Specific methylation was found in cervical cancer (including CDH1, DAPK, MGMT and MINT2), endometrial cancer (CASP8, CDH13, hMLH1 and p73), and ovarian cancer (BRCA1, p14, p15, RIZ1 and TMS1)." (PMID 16928264, 2006). "Additionally, alkylated MGMT suppresses the expression of deubiquitinating enzyme 3 (DUB3), thereby impacting chemoresistance in ovarian cancer." (PMID 38254819, 2024).
ovarian carcinoma (continued). "The investigated gene promoters were chosen from loci previously reported to be methylated in ovarian cancer (n = 7; APC, CDH13, MGMT, MLH1, p14ARF, p16INK4a, RASSF1A) and from loci methylated in other tumour types (n = 6; ADAMTS1, CRABP1, HOXA9, HOXB5, NR3C1, SCGB3A1)." (PMID 17623056, 2007). "Four loci including DAPK, MGMT, p16 and PTEN were selected for methylation analysis in 127 cervical cancers; APC, CDH13, p16 and hMLH1 were examined in 60 endometrial cancers; and BRCA1, p14, p16 and PTEN in 49 ovarian cancers." (PMID 16928264, 2006). "We compared hypermethylation of MGMT, CDH1, RAR-β and SYK promoters in ovarian carcinoma (OC)." (PMID 14970867, 2004). "The pooled OR showed that the methylation of the MGMT promoter was not correlated with clinical stage (OR = 1.46, 95% CI = 0.71–3.02, p = .301), including 223 patients with stage 3–4 and 69 patients with stage 1–2 ovarian carcinoma among four studies." (PMID 29195029, 2018). "Notably, we identified no change in BRCA1 and MGMT mRNA levels in the ovarian cancer patients." (PMID 38542081, 2024).
Alpha-thalassemia (17 papers, 2017 to 2025). Alpha-thalassemia is an inherited hemoglobinopathy characterized by impaired synthesis of alpha-globin chains leading to a variable clinical picture depending on the number of affected alleles. "We also evaluated the protein loss of O-6-methylguanine-DNA methyltransferase (MGMT) and alpha-thalassemia/mental retardation, X-linked (ATRX) during disease recurrence." (PMID 29026176, 2017). "Further genetic testing, including alpha-thalassemia/mental retardation, X-linked (ATRX), telomerase reverse transcriptase promoter (TERTp), and O-6-methylguanine-DNA methyltransferase (MGMT), would be beneficial but was difficult to conduct in this study." (PMID 39917141, 2025). "A statistically significant association of methylated MGMT promoter was observed with isocitrate dehydrogenase-1 (IDH1) protein expression (p = 0.050) and alpha-thalassemia/mental retardation syndrome X-linked (ATRX) loss (p = 0.003)." (PMID 39760063, 2023).
medulloblastoma (16 papers, 1997 to 2025). A malignant, invasive embryonal neoplasm arising from the cerebellum. "Though MGMT expression is primarily regulated epigenetically, a GLI1-binding domain has been identified within the MGMT promoter in medulloblastoma, and Hh inhibition has been linked to MGMT downregulation in GBM cell lines." (PMID 29930746, 2018). "An orally bioavailable selective CK2 inhibitor, CX-4945 (silmitasertib), reduces MGMT expression by blocking β-catenin expression in medulloblastoma and sensitized tumor cells to TMZ." (PMID 35740330, 2022). "The synergistic effect was based on the reduction of β-catenin by CK2-inhibition, which in turn reduced O-6-methylguanine-DNA methyltransferase (MGMT), thereby increasing the sensitivity of medulloblastoma cells to TMZ treatment." (PMID 36009534, 2022). "N3P and N3-sulfoxide analogues also showed promising activity in paediatric medulloblastoma cell lines expressing MGMT and P-gp-mediators of resistance." (PMID 35582280, 2019). "The indication of chemosensitisation observed in this model is therefore encouraging and warrants further investigation in a wider panel of MMR- and MGMT-competent medulloblastoma models." (PMID 20978505, 2010). "The MGMT status of primary medulloblastomas is controversial, with variable estimates in the literature, although in general MGMT defects appear relatively uncommon." (PMID 20978505, 2010). "Hence, we used established H460 NSCLC and D283 medulloblastoma xenografts that continue to express MGMT in nude rat brains." (PMID 33850305, 2022). "In the D283 medulloblastoma orthotopic xenograft model, cranial radiation followed by IV AMON significantly decreased MGMT protein expression compared to radiation only (45.2 ± 8.2 vs. 21.9 ± 6.5 arbitrary unit, p = 0.04)." (PMID 33850305, 2022). "In agreement with the results from medulloblastoma, CX-4945 significantly promoted the anti-tumor efficacy of TMZ, both in vitro and in vivo, by downregulating MGMT and pSTAT3 expression levels in GBM." (PMID 35740330, 2022).
lymph node metastasis (14 papers, 1995 to 2025). "MGMT methylation was strongly associated with lymph node metastasis, lymph invasion, venous invasion, perineural invasion, distant metastasis and relapse." (PMID 37510370, 2023). "In OS and DFS evaluation, the 2-year survival was analyzed according to DAPK and MGMT methylation status, clinical staging and tumor size (T) and lymph node metastasis (N)." (PMID 32870234, 2020). "The frequency of MGMT protein expression was significantly higher in the tumors with no lymph node metastasis compared with the tumors positive for lymph node metastasis." (PMID 24932232, 2014). "While lymph node and skin metastases had similar average MGMT activity, the variance was significantly higher in lymph node metastases." (PMID 7819045, 1995). "Moreover, the methylation of the MGMT promoter is linked to TNM staging, lymph node metastasis, and tumor differentiation in NSCLC." (PMID 40136480, 2025). "Additionally, tumors bearing MGMT methylation had a significant trend toward lymph node metastasis (p = 0.001), lymph invasion (p = 0.005), venous invasion (p = 0.004), perineural invasion (p ≤ 0.001), distant metastasis (p ≤ 0.001) and relapse (p = 0.008)." (PMID 37510370, 2023). "None of the other clinicopathological parameters analyzed, including age, lymph node metastasis, primary tumor location, tumor grade, tumor size, TNM stage, progesterone receptor expression, Her-2 or Ki-67, were significantly associated with MGMT expression (p >0.05)." (PMID 33033516, 2020). "Among NET G1 cases examined, those harboring lymph node metastasis at the time of initial diagnosis had significantly lower MGMT status than those not in primary lesion." (PMID 33287738, 2020). "In the multivariate analysis, MGMT did not demonstrate a correlation with survival, when simultaneously assessed with age, stage, histology, and lymph node metastasis (P=0.16)." (PMID 12085181, 2002).
pancreatic NETs (14 papers, 2017 to 2025). "Of the 37 pancreatic NET specimens, 51% were MGMT-deficient, while, among the 60 extra-pancreatic NET specimens, 0% were MGMT-deficient." (PMID 34638356, 2021). "A retrospective analysis assessed MGMT expression (by immunohistochemistry) in archival NET specimens and compared the prevalence of MGMT deficiency in pancreatic NETs and extra-pancreatic NETs." (PMID 34638356, 2021). "Others demonstrate that MGMT deficiency due to methylation was more prevalent in pancreatic NETs compared to gastrointestinal NETs." (PMID 29255447, 2017). "One patient with MEN1 gene: c.628_631delACAG mutation had grade 3 pancreatic NET (Ki-67 25%) with high MGMT expression, but still derived benefit from CAPTEM therapy with stable disease burden for 3 years after completion of 8 cycles." (PMID 29262620, 2017). "However, the biological importance of MGMT and the mechanism underlying its high expression in pancreatic neuroendocrine tumors (PanNETs) remain elusive." (PMID 39041891, 2024). "MGMT methylation was ever reported to be significantly higher in pancreatic NET (50%) than extra-pancreatic NET (0%–15%), which may partly explain the high efficacy of CAPTEM." (PMID 40438391, 2025). "We constructed stable MGMT‐overexpressing and MGMT‐silenced cell lines using a lentivirus system, and the effect of MGMT on tumor growth was evaluated in an orthotopic pancreatic neuroendocrine tumor model." (PMID 39041891, 2024). "MGMT promoter methylation was reported in 40% of pancreatic NETs, suggesting that this might be a biomarker for response to temozolomide." (PMID 29255447, 2017). "Further investigations have found that approximately 50–70% of pancreatic NETs show negative MGMT expression." (PMID 39061142, 2024). "Moreover, the first large prospective phase II study of TEM in patients with advanced pancreatic neuroendocrine tumors, ECOG‐ACRIN E2211, showed that a lack of MGMT expression by IHC was associated with a superior overall response rate, irrespective of treatment with either TEM or CAPTEM." (PMID 39825572, 2025).
leukemia (13 papers, 2007 to 2025). A malignant (clonal) hematologic disorder, involving hematopoietic stem cells and characterized by the presence of primitive or atypical myeloid or lymphoid cells in the bone marrow and the blood. "Increased MGMT activity is associated with resistance to cancer therapy using an alkylating agent, temozolomide, which has been shown to inhibit cell growth in leukemia cell lines." (PMID 26148869, 2015). "It must be underlined that the majority of preclinical studies on DIX have been conducted on mouse leukemia/lymphoma cells that express low levels of MGMT." (PMID 34639014, 2021). "In detail, these clinical studies showed that lomeguatrib exhibits minimal toxicity and an extremely high suppressing effect on MGMT in leukemia, melanoma, and colorectal cancer." (PMID 34639014, 2021). "Piccioni demonstrated that cisplatin and temozolomide were synergistic in leukemia cell lines, and that in vivo treatment of leukemic patients with cisplatin was followed by a reduction of MGMT activity in peripheral blood mononuclear cells." (PMID 19463179, 2009). "Laboratory studies have shown that only 25% of leukemia cells demonstrate low levels of MGMT." (PMID 19463179, 2009). "Cisplatin depletes MGMT and increases the sensitivity of leukemia cells to temozolomide." (PMID 19463179, 2009).